LEP (leptin)
Diseases named in the same sentence as LEP in open-access papers (continued):
Sharing a sentence is not in itself a finding about the gene and the disease.
Obesity (continued). "The current study clearly showed that characteristics of OA patients and more expecially obesity may affect the responsiveness of cultured chondrocytes to leptin." (PMID 20534145, 2010). "If the central effect of leptin could be by-passed and genes which respond to leptin treatment could be regulated directly, new therapeutic targets for the treatment of obesity may be possible." (PMID 20808936, 2010). "Using leptin/FSP27 double deficient mice as a model system, the expression of BAT-selective genes and regulatory factors was analyzed under the conditions of FSP27 deficiency and obesity." (PMID 20649970, 2010). "Two other leptin-related animal models of obesity exist: db/db mice which lack Ob-Rb but have functional other receptor subtypes, and obese Zucker fa/fa rats bearing mutation within the extracellular domain of the leptin receptor which reduces the affinity for leptin of all receptor isoforms." (PMID 21286276, 2010). "The significant associations between osteoarthritis severity and serum leptin, adiponectin, and IL-1α concentrations, independent of diet and adiposity, support the role of systemic adipokines as mediators of obesity-associated osteoarthritis." (PMID 20604941, 2010). "Consequently, clinical trials using recombinant leptin for the pharmacological treatment of obesity yielded disappointing results." (PMID 20059770, 2010). "By contrast, wild-type mice maintained on a high-fat diet showed no increase in pSTAT3 positive cells in response to leptin (24.2±5.8 cells for vehicle versus 21.8±6.8 cells for leptin, p = 0.8), confirming that diet-induced obesity blunts the leptin-responsiveness of these first-order neurons." (PMID 20613882, 2010). "Leptin reduced the elevated gene expression of tissue-type plasminogen activator (Plat) and lipocalin-2 (Lcn2), which are upregulated in many inflammatory conditions, including human obesity." (PMID 20671928, 2010). "In addition leptin and adiponectin concentrations are determined by the degree of obesity, directly in the case of leptin and inversely in the case of adiponectin." (PMID 20107494, 2010). "Most cases of obesity are associated with leptin insensitivity or resistance, rather than leptin deficiency." (PMID 27713245, 2010). "Analysis of the gut flora in genetically obese (leptin deficient ob/ob) mice and obese humans showed that obesity was associated with a reduction in gram-negative bacteria, specifically Bacteroidetes, and an increase in gram-positive Firmicutes bacteria." (PMID 20454557, 2010). "SH2B1 is a strong prior candidate for regulating body weight; it is implicated in leptin signaling; Sh2b1-null mice are obese; and the evidence suggests that the effects of this gene on obesity are mediated through the central nervous system (see Leptin, hypothalamus and AIS)." (PMID 19878575, 2009). "Leptin, an adipocytokine which is elevated during obesity, may influence gonadal function through modulating steroidogenesis in granulosa cells." (PMID 19849856, 2009). "Background/Aims: Studies in adult population have suggested that leptin might play a role in inducing obesity related hypertension mediated by the sympathetic nervous system." (PMID 21274292, 2009). "However, new evidence shows that elevated leptin levels in the circulatory system contribute to obesity." (PMID 19750222, 2009). "Here, we report that mice lacking AC3 exhibit obesity which is apparently caused by low locomotor activity, hyperphagia, and leptin resistance." (PMID 19750222, 2009). "A variety of adipocyte-derived biologically active molecules have been identified, including leptin, resistin, TNF-α, and IL-6, that may contribute to obesity-linked metabolic abnormalities." (PMID 19254366, 2009). "Overnutrition can blunt central leptin sensitivity before the onset of obesity." (PMID 19606226, 2009).
Obesity (continued). "Since progressive obesity in LY mice is accompanied by the development of insulin and leptin resistance, changes in gene expression may be related to altered metabolic state." (PMID 19650929, 2009). "In contrast, the present study addresses the hypothesis that a maternal calorie-rich diet and consequent obesity lead to hyperphagia in adult offspring through processes involving impaired leptin-signalling and altered neuronal development." (PMID 19516909, 2009). "The decreased locomotor activity, greater food consumption, and leptin resistance exhibited by AC3−/− mice are not caused by obesity since these changes are seen in young, non-obese AC3−/− mice." (PMID 19750222, 2009). "It has been generally thought that leptin resistance is a consequence of obesity." (PMID 19750222, 2009). "Unfortunately, except in the rare cases of leptin deficiency, the clinical application of leptin in humans has not proved to be worthwhile in common obesity, since most obese patients exhibit hyperleptinemia pointing to the existence of leptin resistance." (PMID 19730740, 2009). "Increased levels of leptin have been positively correlated with obesity." (PMID 19208204, 2009). "Although adult AC3−/− mice exhibited elevated leptin levels, it is generally thought that leptin resistance is a consequence of obesity, rather than a cause." (PMID 19750222, 2009). "When stratification by menopausal state and adjustment for plasma leptin concentration was made, results suggest that general obesity assessed by BMI and central obesity measured by WC may both have effects on breast cancer risk." (PMID 19223908, 2009). "Adipose-tissue deriving hormones, such as leptin, which is increased in obesity, may provide an additional mechanism through which adipose tissue may influence Lp-PLA2activity." (PMID 19500354, 2009). "Leptin is called as human Obesity gene and it maps to 7q31.3." (PMID 19772655, 2009). "Post-weaning HFD feeding interacted with maternal obesity to increase plasma leptin and TG concentrations (P<0.05, HFD effect and interaction with maternal obesity); whereas adiponectin was lower and leptin:adiponectin ratio was significantly higher in offspring from small litters (P<0.05)." (PMID 19606226, 2009). "In obesity, there is an expansion of the adipose tissue with increased leptin production." (PMID 19849856, 2009). "Therefore, we believe that the obesity of AC3−/− mice is caused by a combination of lower physical activity, hyperphagia, and decreased leptin sensitivity." (PMID 19750222, 2009). "Interestingly, genes in this module are known to be involved in metabolism and obesity, and include leptin, PPAR-α, and genes involved in the inflammatory response." (PMID 19536287, 2009). "Both animals exhibit obesity, hyperphagia, lower locomotor activity, and leptin resistance." (PMID 19750222, 2009). "Central leptin resistance in obesity and possibly in healthy females." (PMID 19878575, 2009). "This leptin-dependent fine tuning of ovarian function could be of clinical relevance in obesity and related disorders as well as in the pathogenesis of infertility." (PMID 19849856, 2009). "Indeed, in offspring subject to prenatal undernutrition that later develop metabolic dysfunction and obesity, the leptin surge is altered and attenuated, providing further evidence for leptin in the neonatal period as a determinant of later energy balance." (PMID 19746180, 2009). "We conclude that mice lacking AC3 exhibit obesity that is apparently caused by low locomotor activity, hyperphagia, and leptin insensitivity." (PMID 19750222, 2009). "Modulation of ovarian gene expression may involve altered insulin and/or leptin exposure or sensitivity, which is closely related to progressive obesity." (PMID 19650929, 2009). "It has been suggested that programming of leptin concentrations by early diet may be one mechanism that links early nutrition with later obesity." (PMID 19703309, 2009).
Obesity (continued). "A number of polyphenols such as epigallocatechin gallate have anti-obesity activity and may improve metabolic disorders via modulation of adipokines and growth factors, including metabolic improvement of leptin function." (PMID 19254366, 2009). "In anyway, these results indicated that a regulation of leptin and its receptors might be involved in the development of obesity or obesity-related metabolic disorders." (PMID 21566743, 2008). "Interestingly, one of the common abnormal phenotypes in cloned mice is obesity and the concentration of leptin in the blood is usually more than 10 times higher than that of normal mice." (PMID 18398451, 2008). "Thus, in this review, we will describe recent progress made in obesity, visceral adiposity, leptin and adiponectin in the involvement of various cancers." (PMID 21566743, 2008). "In addition, breast cancer cells themselves can synthesize leptin in response to obesity-related stimuli." (PMID 18945363, 2008). "Second, the deletion mice were able to compensate for fasting with the same precision as the WT littermates, and that distinguishes Snord116del mice from other genetic models of obesity, such as ob/ob (leptin-null) mice, or those with hypothalamic neuronal ablation." (PMID 18320030, 2008). "There has been particular interest in the role of leptin in obesity related hypertension." (PMID 20066136, 2008). "Since disruption of the STAT3 binding site on the ObRb results in an obesity syndrome different in numerous aspects from that of complete ObRb deficiency, it is possible that STAT5 may participate in leptin action, as well." (PMID 18286195, 2008). "Some of these effects might be mediated by obesity hormone leptin, acting independently or modulating other signaling pathways." (PMID 18945363, 2008). "The existence of possible genetic, biological and physical mechanisms (like gastroesophageal reflux) or chemical mechanisms (inflammatory substances like tumor necrosis factor alpha, leptin or adiponectin) that are common to asthma and obesity has been observed." (PMID 19099163, 2008). "Similar to fat pad weights, Obesity-Resistant mice had serum leptin levels that were twice those of Low-Fat diet mice; again, this difference was not significant using the Newman-Keuls test following ANOVA but was significantly different when compared by the Student t test (p < 0.03)." (PMID 18162139, 2007). "Of the circulating factors increased in obesity – including leptin, insulin, NEFAs and TGs – only the latter two are raised by short-term high-energy feeding (prior to obesity onset), suggesting they may play the more critical role." (PMID 17570846, 2007). "While systemic leptin is increased in obesity, adiponectin is reduced." (PMID 17311679, 2007). "(iii) Several rodent models of leptin resistant obesity exhibit increased Socs3 expression." (PMID 17445271, 2007). "From a medical standpoint, the significance of understanding Agrp transcriptional regulation stems from the observation that common obesity is characterized by a blunted central response to peripheral energy signals, a phenomenon referred to as leptin resistance." (PMID 17684549, 2007). "Determination of the leptin and NPY concentrations provided evidence that obesity represents disease with neuroendocrine dysfunction and high leptin/NPY ratio, which could be a useful marker for central obesity." (PMID 17721641, 2007). "Proliferative and anti-apoptotic responses of the Barrett's epithelium to the increased serum leptin levels seen in obesity may be an important mechanism in the link between increased body mass index and OAC." (PMID 17559672, 2007). "In human beings, serum leptin concentration is directly proportional to body fat mass, but it is leptin resistance and not leptin deficiency per se which is regarded as a pathogenic mechanism in human obesity." (PMID 17617917, 2007). "One link between obesity and breast cancer is the adipokine, leptin." (PMID 18162139, 2007).
Obesity (continued). "Increases in serum leptin observed in obesity may contribute to the increased incidence of asthma in the obese because leptin, a member of the IL-6 family of cytokines, has pro-inflammatory effects." (PMID 16581558, 2006). "They suggest high maternal BMI may lead to greater circulating glucose in fetuses and altered adipocyte metabolism during childhood, ultimately leading to greater leptin levels in adulthood and a propensity towards obesity." (PMID 16942616, 2006). "Furthermore, handling is shown to prevent other maladaptive states such as stress-induced hyperphagia, obesity and resistance to leptin." (PMID 15876359, 2005). "To date, experimental approaches to the investigation of this novel link between obesity and immune function have been predominantly carried out in genetic models of obesity that either lack leptin (ob/ob mouse) or the long form of the leptin receptor (db/db mouse)." (PMID 15813957, 2005). "Although the SNPs involved in energy homeostasis investigated in our study did not modify the risk of NHL associated with obesity, independent effects were seen for FL with the LEP 19G>A and LEP −2548G>A SNPs, irrespective of adiposity." (PMID 16160698, 2005). "As circulating levels increase, leptin acts to modulate food intake, but in obesity, its rise with increasing body fat has limited effect on satiety, suggesting negative regulators of leptin and insulin signalling, such as leptin receptor and adiponectin, are present." (PMID 16160698, 2005). "Leptin, a peptide related to obesity, also affects β-amyloid regulation." (PMID 16321166, 2005). "In most human obesity cases, as well as in model animals e.g. mice, obese individuals displayed elevated plasma leptin levels compared to subjects of normal weight, thus demonstrating "leptin resistance"." (PMID 16300680, 2005). "The aminoguanidine carboxylate, BVT.12777, is one of a series of structurally related molecules based on the anti-diabetic/anti-obesity agent 3-guanidinopropionic acid, which, like leptin, have been demonstrated to reduce body weight in obese diabetic (ob/ob) mice." (PMID 15329154, 2004). "Together, all of these features suggest a state of "leptin resistance" which may ultimately lead to obesity and metabolic syndrome." (PMID 15530168, 2004). "The changes in leptin and ghrelin with sleep restriction could, therefore, provide a powerful dual stimulus to food intake that may culminate in obesity." (PMID 15602591, 2004). "Other adipokines, such as leptin, are important in obesity and insulin resistance." (PMID 15491498, 2004). "However, despite the lack of significant associations between leptin and cardiovascular risk, the researchers showed a negative correlation between ghrelin and adiponectin and systolic blood pressure in patients with obesity." (PMID 41596212, 2026). "Additionally, obesity is often associated with a series of cardiovascular diseases such as hypertension, and leptin serves as a key mediator linking obesity to hypertension, primarily participating in blood pressure regulation through central sympathetic nerve activation." (PMID 41503874, 2026). "In addition to leptin, other cytokines also play important roles in obesity." (PMID 41503874, 2026). "Similarly, leptin resistance exhibits a bidirectional relationship with obesity." (PMID 41596611, 2026). "Additionally, obesity—typically quantified by body mass index (BMI)—represents a well-established DKD risk factor that promotes renal damage through mechanisms such as hyperfiltration, leptin resistance, and chronic inflammation." (PMID 41601932, 2026). "Although our understanding of the disease of obesity is still evolving, within the context of this paper we consider the disease a manifestation of the pathophysiological processes when the expression of leptin resistance leads to the establishment of a new, higher adipose mass set point." (PMID 41268722, 2026).
Obesity (continued). "Leptin levels differ significantly between adult men and women, it is unknown whether these sex differences arise during puberty in children with normal weight (NW) or overweight (OW)/obesity (OB)." (PMID 41240372, 2026). "Mendelian randomization analyses (using genetic proxies for leptin) have not found a clear causal role for leptin in coronary or stroke risk (e.g., OR ≈1.48; 95% CI 0.78–2.80), suggesting leptin might be a marker of obesity rather than an independent cause." (PMID 41567175, 2026). "The net effect of this for animals and humans alike, whether lean or with obesity, is to increase meal size, meal frequency, or both as part of the adaptation in changes in gut hormone and leptin levels and receptor signaling following diet‐induced weight loss." (PMID 41268722, 2026). "In addition, our results provide support for using the leptin/adiponectin ratio as an index of adipose tissue dysfunction, showing a strong association with BMI in participants without obesity." (PMID 41528263, 2026). "Thus, as observed in our data, animals in the OB‐SD group have higher serum leptin concentrations; in fact, leptin may be one of the drivers of sympathetic nervous system hyperactivity in obesity." (PMID 40842420, 2025). "Furthermore, exploring possible epigenetic and microRNA-mediated processes that regulate the expression of CART, leptin, and eNOS may reveal further information on the molecular interactions between obesity, metabolic regulation, and reproductive health." (PMID 40002424, 2025). "However, although deleting Ptpn11 in subsets of hypothalamic Lepr neurons causes mild obesity and impaired glucose homeostasis, it does not attenuate the acute anorexic effects of leptin." (PMID 40393800, 2025). "Then, potential effects of CCJ12 on adipokines (leptin and adiponectin), cardiovascular (sE-selectin and C-reactive protein), and inflammatory (MCP-1 and TNF-alpha) factors were studied, because these factors are also associated with obesity as well as other diseases." (PMID 40770283, 2025). "Mouse models of BBS have demonstrated leptin resistance in the hypothalamic MC4R pathway, which drives hyperphagia and obesity and may be explained by impaired leptin signaling in the hypothalamic neurons resulting from disrupted functioning of the neuronal cilia." (PMID 40186386, 2025). "Additionally, obesity-induced decreases in adipokines such as leptin, along with elevated lipid and glucose levels, may exacerbate these processes." (PMID 39996061, 2025). "Because of that, brain leptin resistance could be the potential link between obesity and AD." (PMID 40498212, 2025). "Obesity is associated with the presence of prothrombotic factors (e.g., fibrinogen, homocysteine), inflammatory markers (e.g., interleukin-6 (IL-6), tumor necrosis factor-alpha (TNF-α), C-reactive protein (CRP)), and adipocytokines (e.g., leptin, adiponectin))." (PMID 39857920, 2025). "While this may seem paradoxical, given that leptin is a hormone involved in appetite suppression and fat oxidation, it is important to note that leptin is primarily secreted by adipocytes, and its circulating levels are typically elevated in individuals with obesity due to leptin resistance." (PMID 40507170, 2025). "Therefore, improving leptin sensitivity is an important therapeutic target in addressing obesity." (PMID 40104296, 2025). "From a practical standpoint, this means that higher fat and caloric contents, leptin loads, adenine levels, or mannose concentrations combined with higher intakes due to decreases in the satiety of infants are more likely to influence infant obesity than milk oligosaccharides." (PMID 39861468, 2025). "Also, the increased circulating lipoproteins in obesity stimulate TLR2, causing adipocytes and macrophages to secrete less adiponectin and to produce pro-inflammatory cytokines, predisposing to leptin resistance in the central nervous system and insulin resistance peripherally." (PMID 39837875, 2025).